APOE (apolipoprotein E)
Diseases named in the same sentence as APOE in open-access papers (continued):
Sharing a sentence is not in itself a finding about the gene and the disease.
atherosclerosis (continued). "Recently, using genome editing techniques, APOE-knockout rabbits have been created as a novel rabbit model for the study of hyperlipidemia and atherosclerosis." (PMID 29099857, 2017). "The miR-144-3p target ABCA1 is involved in the progression of atherosclerosis via the promotion of proinflammatory cytokine production in apolipoprotein E KO (apoE-/-) mice." (PMID 29050208, 2017). "ApoE-/- mice have been shown to develop severe hypercholesterolemia and atherosclerosis lesions that are more characteristic in appearance and distribution to those observed in humans." (PMID 29354055, 2017). "Sprr3-/- mice were primarily evaluated on the ApoE-/- background to induce hyperlipidemia and atherosclerosis progression." (PMID 28886156, 2017). "We evaluated the vasoactive effects of Up4A on CF in atherosclerosis using ApoE knockout (KO) mice ex vivo and in vivo." (PMID 28929376, 2017). "Taking into consideration various biological activities of bee pollen ingredients, the aim of the current study was to determine the effect of polyphenol-rich EEP on atherosclerosis induced by a high-fat diet in ApoE-knockout mice." (PMID 29258230, 2017). "The ratio of plaque to vessel wall area in ApoE-/- mice increased from 8 to 32 weeks (Spearman rank correlation coefficient 0.92; P<0.001), indicating the progression of atherosclerosis in ApoE-/- mice." (PMID 28982198, 2017). "In contrast, when challenged with a Western diet, Plpp3f/f apoE−/− Alb-Cre+ mice showed a 35% increase in atherosclerosis development, as compared with Plpp3f/f apoE−/− Alb-Cre- mice (p = 0.031)." (PMID 28291223, 2017). "Hla and co-workers reported that selective endothelial cell specific S1pr1 KO induced in juvenile ApoE KO mice resulted in enhanced HF diet-induced atherosclerosis." (PMID 29244772, 2017). "Our network analysis also uncovers atherosclerosis and ApoE as the most relevant disease and upstream regulator, respectively, confirming that DHI is able to inhibit the development of atherosclerosis in ApoE−/− mice." (PMID 29133791, 2017). "In the present study, we have elucidated the role of EGFR in high-fat diet-induced atherosclerosis in apolipoprotein E null mice." (PMID 28374780, 2017). "In agreement with the atheroprotective phenotype observed in our DKO mice, the genetic inactivation of P2y1 in ApoE KO mice also results in platelet hyporeactivity and protection from atherosclerosis." (PMID 28487312, 2017). "Bone marrow transplantation studies revealed the importance of macrophage–secreted apoE in the protection against atherosclerosis." (PMID 28355284, 2017). "Using this pure antigen, we established a purified MAA-ELISA, with which a marked increase in anti-MAA antibody titer was determined at a very early stage of atherosclerosis in 3-month ApoE-/- mice fed with a normal diet." (PMID 28222187, 2017). "In contrast to our findings, high LET radiation exposure has been shown to increase the in vitro expression of adhesion molecules, which can lead to accelerated development and progression of atherosclerosis in obese apoE−/−mice." (PMID 28993729, 2017). "In ApoE KO mice hyperlipidemia contributes to atherosclerosis, with ApoE KO AdvSCA-1+ cells displaying enhanced cell migration." (PMID 28757161, 2017). "To investigate the effect of IL-37 on atherosclerosis, we treated ApoE−/− mice with recombinant human IL-37 protein." (PMID 28607385, 2017). "The inhibition of 11β-HSDH1 decreased weight gain, food intake, and fat pad weight in murine models of diet-induced obesity (DIO) and type 2 diabetes mellitus and in a mouse model of atherosclerosis, the apolipoprotein E (ApoE) knockout mouse." (PMID 28386270, 2017). "In ApoE-KO mice, the blocking of α4 integrin inhibits the recruitment of peritoneal macrophages in atherosclerosis." (PMID 28241014, 2017).
atherosclerosis (continued). "Previous studies reported that oxLDL actives mammalian target of rapamycin (mTOR) in THP-1cell, and an activator of mTOR inhibits oxLDL-induced autophagy and restricts atherosclerosis in ApoE-knockout mice." (PMID 28777810, 2017). "Accordingly, deficient mice of B1-kinin receptor has been described to aggravate atherosclerosis and the development of abdominal aorta aneurysms in ApoE−/− mice under cholesterol rich-diet." (PMID 28503149, 2017). "In this study, we document that the mice with specific overexpression of mitoNEET in brown adipocytes (mitoNEET-Tg) are cold resistant and partially resistant to the development of atherosclerosis in an ApoE knockout background." (PMID 29311966, 2017). "On the other hand, selective inactivation of the S1PR2 in bone marrow (BM)-derived cells has been reported to suppress atherosclerosis development in ApoE KO mice, due to suppression of inflammation." (PMID 29244772, 2017). "The selective Mas receptor agonist AVE0991 exhibited anti‐atherosclerotic and anti‐inflammatory actions, affecting monocyte/macrophage differentiation and recruitment to the perivascular space during early stages of atherosclerosis in ApoE−/− mice." (PMID 27935022, 2017). "In this study, we demonstrated that GF ApoE−/− mice are resistant to the development of atherosclerosis." (PMID 28130274, 2017). "To evaluate the effect of QSYQ on the development of atherosclerosis, we treated 8w male ApoE-/- mice with a low dose (human equivalent) or high dose (five times of human equivalent) QSYQ for 8 weeks." (PMID 29137256, 2017). "The development of atherosclerosis in ApoE(-/-) mice occurs over weeks compared to several decades in humans." (PMID 29091929, 2017). "Hypercholesterolemic mice, deficient in both HMOX1 and ApoE (HMOX1−/−/ApoE−/−), demonstrated enhanced development of atherosclerosis compared to ApoE−/− single knockout mice." (PMID 29104732, 2017). "Our group has demonstrated that AnxA5 reduces inflammation in advanced atherosclerosis and contributes to stabilization of the advanced plaques in the ApoE-/- mouse model of atherosclerosis." (PMID 29267398, 2017). "A recent report showed that aged ApoE−/− and ApoE−/− /p47phox−/− mice that developed atherosclerosis and vascular dysfunction were characterized by mitochondrial dysfunction related with an upregulated expression of NOX4 in VSMCs." (PMID 28230726, 2017). "We have previously shown that MGL affects plaque stability in apolipoprotein E (ApoE)−/− mice, an established animal model for dyslipidemia and atherosclerosis." (PMID 28380440, 2017). "Previous studies have suggested that Icariin attenuated the development of atherosclerosis in several animal models, including ApoE-/- mice, rats, and rabbits." (PMID 29075193, 2017). "En-face analysis of the entire aorta of the Western diet-fed mice showed a dramatic increase in aortic atherosclerosis in Plpp3f/f apoE−/− Alb-Cre+ mice, specifically in the aortic arch and the thoracic segment, as compared with Plpp3f/f apoE−/− Alb-Cre− mice." (PMID 28291223, 2017). "Treatment of apoE−/− mice with varespladib resulted in the reduction of atherosclerosis development and a more stable plaque phenotype." (PMID 28409825, 2017). "Aortic function was studied using wire myography, and atherosclerosis was induced by fat-feeding ApoE−/− mice." (PMID 28365690, 2017). "In vivo experiments in atherosclerosis mice models, such as apolipoprotein-E knockout mice (ApoE−/−) would shed some light on this promising therapeutic application of puupehenones." (PMID 29065486, 2017). "Our results identified CRAMP, the mouse homolog of hCAP-18, as a potential self-antigen involved in the immune response to atherosclerosis in the ApoE(-/-) mouse model." (PMID 29091929, 2017).
atherosclerosis (continued). "Another recent study in ApoE-KO mice showed that probiotic mixture VSL#3 can protect from atherosclerosis." (PMID 28609252, 2017). "In conclusion, prolonged administration of agmatine inhibits atherosclerosis in apoE-/- mice; however, the exact mechanisms linking observed changes and elevations of HDL plasma require further investigation." (PMID 28777310, 2017). "In ApoE (-/-) mice with HFD-induced atherosclerosis, the elevated expression of pro-apoptosis factors caspase-3, caspase-9 and Bax and the decreased level of anti-apoptosis factor Bcl-2 were induced by miR-210 overexpression." (PMID 28536634, 2017). "Considering the multiple positive effects of apoE against atherosclerosis, various strategies to increase its expression were designed." (PMID 28355284, 2017). "Parenteral administration of enoxaparin (FXa/IIa inhibitor) and fondaparinux (FXa inhibitor) over 14 days reduced to severity of aortic aneurysm and atherosclerosis in AngII-infused ApoE−/− mice." (PMID 28220880, 2017). "A role of Irisin in improving endothelial function via the AMPK-eNOS pathway is also noteworthy in obese mice and it also has a protective role against ED and atherosclerosis in apolipoprotein E-Null (apoE(−/−)) diabetic mice." (PMID 28750629, 2017). "ApoE-/- mice, in which the targeted deletion of the apoE gene leads to severe hypercholesterolemia and spontaneous atherosclerosis, are among the most widely used mouse models for atherosclerosis." (PMID 28166283, 2017). "The major finding of this study is that systemic overexpression of Ang-1 accelerates atherosclerosis development in ApoE-/- mice." (PMID 28069704, 2017). "In conclusion, this meta-analysis suggests that flavonoids reduced the severity of atherosclerosis in ApoE-/- mice." (PMID 28742839, 2017). "Studies investigating the direct effects of n-3 PUFAs on apoE expression and function are scarce since the most commonly used atherosclerosis model is the apoE knockout mouse." (PMID 28984832, 2017). "Together, these data demonstrate that atherosclerosis burden of mdx-ApoE mice is equal to or less than that of ApoE mice and therefore likely does not account for the extent of muscle damage observed in mdx-ApoE mice." (PMID 28899419, 2017). "The present study aims to investigate the vasculoprotective effect of chP3R99 administration in an advanced atherosclerosis setting in apoE-/- mice and to characterize the main mechanisms involved." (PMID 29163168, 2017). "Apolipoprotein E (ApoE) is a 34-kDa secreted protein that has been shown to have anti-atherosclerosis activity: it targets abundant lipoproteins in arteries and is capable of efficiently removing them." (PMID 28536634, 2017). "Hemizygous deletion of Cd39 (Cd39+/−) on ApoE KO atherosclerotic background results in heightened platelet activation and consequent worsening of atherosclerosis." (PMID 28487312, 2017). "To assess this, we used the ApoE−/− mouse model of atherosclerosis under physiological and atherogenic conditions." (PMID 28752048, 2017). "We therefore studied the impact of dissecting the plaque draining lymph vessels and lymph node on atherosclerosis development in ApoE−/− mice." (PMID 28349940, 2017). "Taking all these results into consideration, we used orally active, selective Mas receptor agonist AVE0991 to stimulate the Ang‐(1‐7) protective axis in ApoE‐/‐ mice, and studied its effects on atherosclerosis and vascular inflammation." (PMID 27935022, 2017). "The substantial role of angiotensin II in atherosclerosis progression has been demonstrated in AT1-/-/ApoE-/- mice that exhibited diminished atherosclerotic burden and vascular ROS production." (PMID 28688452, 2017).
atherosclerosis (continued). "Our study indicates that exogenous agmatine, used for four months, significantly inhibits the development of atherosclerosis in apoE-knockout mice." (PMID 28777310, 2017). "Administration of a recombinant soluble form of RAGE consisting of the extracellular AGE-binding domain, has not only suppressed the development of atherosclerosis but also stabilized established atherosclerosis in diabetic apolipoprotein E-null mice." (PMID 28259164, 2017). "eNOS overexpression in apolipoprotein E knockout mice was reported to accelerate the development of atherosclerosis." (PMID 28427390, 2017). "Previous studies have demonstrated that targeting solely VSMC apoptosis in the setting of atherosclerosis induced by HFD in ApoE-/- mice can generate key features of unstable plaques, including thin fibrous caps." (PMID 28886156, 2017). "Pharmacological inhibition or knockdown of HO-1 show significant increases in lesion formation and further accelerates atherosclerosis in ApoE null mice, Watanabe heritable hyperlipidemic rabbits (WHHL) and aortitis in chow-fed old C57BL/6 mice." (PMID 29113088, 2017). "Previous reports have established that dietary phosphatidylcholine is metabolized by gut flora into choline and trimethylamine N-oxide (TMAO), both of which increase atherosclerosis in apolipoprotein E knockout mice (apoE-/- mice)." (PMID 29240800, 2017). "Up-regulation of CFTR attenuated immune cells infiltration and vascular inflammation as well as atherosclerosis development in apoE−/− mice." (PMID 28615349, 2017). "We investigated the effects of AVE0991 on the spontaneous atherosclerosis in apolipoprotein E (ApoE)−/− mice, in the context of vascular inflammation and plaque stability." (PMID 27935022, 2017). "To date, there is disagreement concerning the APOE role on atherosclerosis involving the carotid and lower limb arteries." (PMID 28249002, 2017). "The ApoE-/- mouse model is particularly useful for studying atherosclerosis due to its quick and predictable development of atherosclerosis." (PMID 28742839, 2017). "To identify the therapeutic activity of rebamipide, we induced atherosclerosis in ApoE knockout mice and determined the atherogenesis reducing activity of rebamipide by evaluating the levels of inflammatory cytokines or serum lipids in vivo or in vitro." (PMID 28241014, 2017). "Next, we investigated potential protective effects of cortistatin in a model of chronic atherosclerosis in apoE−/− mice fed a high-lipid Western diet for 16 weeks." (PMID 28406244, 2017). "Investigations of ApoE (-/-) mice have verified the crucial role of ApoE in protection from atherosclerosis." (PMID 28536634, 2017). "We used an adenoviral vector to overexpress C5a in ApoE−/− mice to determine the effects of a brief elevation in C5a protein in established atherosclerosis." (PMID 27517153, 2016). "In this report, we demonstrate that both acute and chronic BM-573 treatments improve the endothelial dependent relaxation and prevent the increase of systolic blood pressure in ApoE-KO mice at early stages of atherosclerosis." (PMID 27019366, 2016). "In a model of atherosclerosis, Cav1 whole body knockout mice were crossed to ApoE knockout mice, leading to a reduction in aortic plaque burden." (PMID 27027326, 2016).
atherosclerosis (continued). "Treatment with recombinant IL-6 in atherosclerosis-prone ApoE−/− mice resulted in aggravated atherosclerotic state which was accompanied by increased levels of other pro-inflammatory cytokines and APPs." (PMID 27166190, 2016). "Induction of diabetes with STZ has been performed in different atherosclerosis models, and especially in ApoE−/− mice." (PMID 27618031, 2016). "The results indicated that the expression patterns of PPAR α, PPAR γ, ROR α, and RXR α in mice were altered in ApoE-KO mice, which would promote atherosclerosis progression." (PMID 27631008, 2016). "We show that ApoE−/− mice, which spontaneously develop hyperlipidemia and atherosclerosis, also exhibit a heightened level of inflammatory arthritis when compared to control mice." (PMID 27287704, 2016). "In vivo studies have revealed that the administration of GLP-1 analogues or DPP-4 inhibitors reduces high-fat-diet-induced atherosclerosis and stabilizes plaques in apoE knockout mice." (PMID 27351380, 2016). "Here we tested the effect of two inhibitors of phosphatidylinositol 3-kinase, 3-methyladenine (3-MA) and 2-(4-morpholinyl)-8-phenyl-chromone (LY294002), commonly used as inhibitors of autophagy, in atherosclerosis in apolipoprotein E−/− mice." (PMID 27906187, 2016). "We also examined the effects of CNTs on atherosclerogenesis and analyzed their effects on the function of EPCs isolated from the bone marrow of ApoE−/− mice, a model of human atherosclerosis." (PMID 27737702, 2016). "Using high fat diet induced atherosclerosis in ApoE−/− mouse, we generated Adamts4 and ApoE double knockout mice (ApoE−/−Adamts4−/−)." (PMID 27491335, 2016). "Huang and colleagues demonstrated that L. acidophilus ATCC 4356 prevents atherosclerosis by inhibition of intestinal cholesterol absorption in ApoE-/- mice." (PMID 27120199, 2016). "The effects of defective glucokinase on the glucose metabolism and on the progression and regression of atherosclerosis on high-fat diets were studied in both genders of GK+/−ApoE−/− and ApoE−/− mice." (PMID 27774459, 2016). "ApoE-KO mouse is an ideal model of atherosclerosis, in which total serum cholesterol and low-density lipoprotein levels are significantly higher than in C57 mice of the same sex." (PMID 27631008, 2016). "We conducted PM2.5 exposure specifically on 16-week ApoE−/− mice in order to examine the toxicological effect of instillation exposure to PM2.5 on the development of atherosclerosis at initial stages." (PMID 27187431, 2016). "The present study demonstrated that equol intervention inhibited the development of atherosclerosis plaques in HFD-fed apoE-/- mice." (PMID 27907038, 2016). "Atherosclerosis in ApoE−/− mice is driven by impaired clearance of cholesterol-enriched lipoproteins, which results in elevated levels of plasma cholesterol and atherogenic remnants." (PMID 27721472, 2016). "In particular, ApoE−/− mice are currently the most well-characterized mouse model of atherosclerosis used by research groups worldwide." (PMID 27618031, 2016). "Atherosclerotic plaque formation was increased in apolipoprotein E knockout transgenic mice (ApoE–/–; mouse model of atherosclerosis) when the mice were supplemented with L-carnitine." (PMID 27714645, 2016). "This study investigates the impact of RDN on aortic compliance in a novel atherosclerosis prone ApoE−/−-rat model." (PMID 27277003, 2016). "The study of multiple disease endpoints in one mouse model would be very advantageous, as seen in a study of hyperlipidemic APOE*3-Leiden mice, which are prone to atherosclerosis." (PMID 27207171, 2016). "Clock/ApoE double knockout mice also exhibit increased atherosclerosis and lipid laden macrophages compared to atherosclerosis prone mice with a functional clock." (PMID 27168152, 2016). "In our results, miR-92a levels were significantly decreased in ApoE-/- mice fed a high methionine diet as well as in Hcy treated foam cells, suggesting that miR-92a was involved in Hcy induced atherosclerosis." (PMID 27936205, 2016).